ENSG00000199231
Synonyms: LOC124901826
Gene: Small nucleolar RNA gene on chromosome 7 (63,175,940 to 63,176,019, reverse strand). Ensembl gene ENSG00000199231.
Gene Ontology:
Biological process: RNA processing
Cellular component: nucleolus
Homologues: Orthologues: rat LOC120100395 (79% identical), rat LOC120094475 (78% identical), mouse Gm24339 (74% identical).